METTL3 (methyltransferase 3, N6-adenosine-methyltransferase complex catalytic subunit)
Diseases named in the same sentence as METTL3 in open-access papers (continued):
Sharing a sentence is not in itself a finding about the gene and the disease.
cervical cancer (continued). "The expression of METTL3 was up-regulated in cervical cancer although no statistical significance was achieved." (PMID 32201509, 2020). "Furthermore, the mRNA expression of TGFB1 was negatively correlated with the expression of METTL3, while positively correlated with the expression of SNAI1 in 169 cases of cervical cancer patients." (PMID 31991845, 2020). "The m6A methyltransferase METTL3 links to the 3’-untranslated region of HK2 mRNA and recruits YTHDF1 to ensure HK2 stability, ultimately boosting aerobic glycolysis in cervical cancer (CC) cells, contributing to their proliferation and leading to poor prognosis in cervical cancer." (PMID 37055798, 2023). "We then used nude mice to construct cell line-derived xenograft subcutaneous tumor models and found that METTL3 staining was darker in Siha (HPV positive cervical cancer cell line)-derived tumors than in C33A (HPV negative cervical cancer cell line)-derived tumors." (PMID 35813476, 2022). "iASPP and METTL3 expression in the tumor specimens and adjacent non-tumor cervical tissues was determined by immunohistochemistry and western blot, and its relationship with clinicopathologic factors and prognosis of cervical cancer patients was analyzed." (PMID 32201509, 2020). "However, the expression of METTL3 and the relationship between METTL3 expression and clinicopathological characteristics or prognosis of cervical cancer have not been shown." (PMID 32201509, 2020). "However, the correlation between iASPP and METTL3 is not clearly defined in cervical cancer." (PMID 32201509, 2020).
lung adenocarcinoma (72 papers, 2018 to 2026). A carcinoma that arises from the lung and is characterized by the presence of malignant glandular epithelial cells. "Another study found that upregulation of METTL3 is not only associated with longer overall survival (OS) in lung adenocarcinoma, but also associated with better recurrence-free survival (RFS)." (PMID 34814861, 2021). "Additionally, we assessed the extent of methylation at 2515th adenine residue in metastasis-associated lung adenocarcinoma transcript (MALAT) long noncoding RNA (lncRNA) upon METTL3 knockdown." (PMID 39594581, 2024). "A recent study has discovered that the expression of the two components of xCT system, SLC3A2 and SLC7A11, can be modulated by proteins involved in m6A modification, YTHDC2 and METTL3, leading to the induction of ferroptosis in lung adenocarcinoma cells." (PMID 41339932, 2025). "METTL3 inhibits malignant progression of lung adenocarcinoma by blocking the PI3K/AKT/NF-κB signaling pathway." (PMID 41256854, 2025). "The ceRNA mechanism is also evident in lung adenocarcinoma through the miR-590-5p/METTL3 axis and in prostate cancer via modulation of PRMT5 through miR-376a-3p." (PMID 40903777, 2025). "It has been reported that m6A modification of FBXW7 mRNA by METTL3 upregulates FBXW7 protein levels in lung adenocarcinoma." (PMID 40169588, 2025). "For example, in lung adenocarcinoma, METTL3-dependent m6A modification in the CDS of FBXW7 mRNA promotes its translation." (PMID 38444581, 2024). "The results showed that METTL3 was substantially up-regulated in both lung adenocarcinoma (LUAD) and lung squamous cell carcinoma (LUSC) patients compared with control subjects." (PMID 39309428, 2024). "For example, the enrichment of METTL3 in lung adenocarcinoma activated a decrease in SLC7A11 m6A levels, which in turn impeded cell ferroptosis and accelerated tumor progression." (PMID 38221933, 2024). "In lung adenocarcinoma, METTL3-mediated m6A modification enhances SLC7A11 translation, fostering cell proliferation while suppressing cell ferroptosis, a nonapoptotic form of cell death known for selective elimination of tumor cells." (PMID 38444581, 2024). "Knockdown of lncRNA NUTM2A-AS1 suppresses lung adenocarcinoma cell viability and induces apoptosis through the miR-590-5p/METTL3 axis." (PMID 37542290, 2023). "The expression of METTL3 was significantly up-regulated in lung adenocarcinoma, which promoted the malignant proliferation, migration and invasion of lung adenocarcinoma cells." (PMID 38028153, 2023). "METTL3 and circKRT17 levels are elevated in osimertinib-insensitive lung adenocarcinoma tissues and cells." (PMID 37996892, 2023). "In lung adenocarcinoma, METTL3-mediated m6A modification of ENO1 at 359A stimulates glycolysis and tumorigenesis." (PMID 37996892, 2023). "Further exploration data displayed that LncRNA AC098934 promoted the malignant behavior of lung adenocarcinoma cells under the m6A modification induced by METTL3." (PMID 37365581, 2023). "Elevated METTL3 expression was observed in human lung adenocarcinoma, where METTL3 played an essential role in promoting cancer cell survival, proliferation and invasion." (PMID 37612540, 2023). "In lung adenocarcinoma, significantly low expression of METTL3 inhibits m6A modification and translation of the E3 ubiquitin ligase FBXW7, resulting in reduced levels of ubiquitination and degradation of oncogenes such as MYC, accelerating tumor metastasis." (PMID 37996892, 2023). "Data from the TCGA database showed that the mRNA expression of METTL3 is significantly elevated in lung adenocarcinomas (LUAD)." (PMID 35672673, 2022). "Researchers have found that METTL3 is highly expressed in lung adenocarcinomas, while METTL3-silenced cells proliferate and migrate much less than those that are not silenced." (PMID 36386128, 2022).
lung adenocarcinoma (continued). "Researchers have found that METTL3 is associated with longer survival in patients with lung adenocarcinoma, and METTL3 can be used as a biomarker to predict the prognosis of lung adenocarcinoma." (PMID 34814861, 2021). "In a recent investigation, METTL3 expression was significantly upregulated in patients with lung adenocarcinoma." (PMID 33902609, 2021). "METTL3 can promote growth, survival, and invasion by interacting with the translation initiation element to enhance mRNA translation in lung adenocarcinoma." (PMID 34568001, 2021). "Studies have found that the METTL3 expression is upregulated in human lung adenocarcinoma cell lines." (PMID 34814861, 2021). "Another research team found that in human lung adenocarcinoma cell lines, METTL3 can promote the translation of oncogenes, thereby promoting tumor cell survival, proliferation and invasion." (PMID 34814861, 2021). "METTL3 was higher expressed in lung adenocarcinoma tissues than that of paired normal tissues, and was involved in the gefitinib resistance of NSCLC cells." (PMID 33177491, 2020). "METTL3 mediated YAP1 m6A modification promotes liver metastasis of lung adenocarcinoma." (PMID 40097750, 2025). "For instance, in lung adenocarcinoma cells, METTL3, through its m6A methyltransferase activity, mediates the m6A modification of JUNB mRNA, which enhances mRNA stability and promotes its nuclear translocation as a transcription factor to activate downstream gene expression." (PMID 40299340, 2025). "METTL1, METTL3, METTL4, METTL5, METTL6 and METTL13 were associated with poor prognosis in various tumors including liver hepatocellular carcinoma (LIHC), breast invasive carcinoma (BRCA), and lung adenocarcinoma (LUAD)." (PMID 41194259, 2025). "METTL3 plays a crucial role in regulating lung adenocarcinoma (LUAD) and hepatoblastoma." (PMID 40271153, 2025). "In lung adenocarcinoma and hepatoblastoma, METTL3-mediated m6A modification could suppress ferroptosis and promote tumor progression by regulating SLC7A11 mRNA stability and translation." (PMID 40175350, 2025). "Notably, METTL3 enhances the development of lung adenocarcinoma, likely through the promotion of tumour occurrence and the inhibition of cell iron death by upregulating SLC7A11 expression." (PMID 39580709, 2024). "In addition, high expression of LncRNA SVIL-AS1, of which expression is also upregulated by METTL3-mediated m6A modification, can promote the occurrence and development of lung adenocarcinoma." (PMID 37365581, 2023). "For instance, in lung adenocarcinoma, high HNRNPC and IGF2BP3 levels correlate with reduced overall survival, and a six-gene risk signature (KIAA1429, ALKBH5, METTL3, HNRNPC, YTHDC2, and YTHDF1) strongly correlated with various clinical and pathological features." (PMID 36831575, 2023). "For example, METTL3 increased m6A modification of PCAT6, resulting in PCAT6 upregulation in an IGF2BP2-dependent manner; LCAT3 stability was significantly increased in a METTL3-dependent manner in lung adenocarcinomas, thereby activating MYC transcription via FUBP1." (PMID 35037556, 2022). "In addition, another study in lung adenocarcinoma (LUAD) demonstrated that METTL3 enhances RNA stability and promotes translation of SLC7A11 through m6A-mediated binding of YTHDF1 and YTHDC2, YTHDC2 prefers to bind to m6A-modified SLC7A11 mRNA and promoting its decay." (PMID 39799112, 2025). "Moreover, METTL3 also upregulates the level of miR-1246 which reduces the expression of the tumor suppressor PEG3 to promote the development of lung adenocarcinoma; In addition, METTL3 can also promote tumor proliferation, EMT, invasion, and migration by down-regulating miRNAs, such as: miR-1915-3p." (PMID 35784761, 2022). "In lung adenocarcinoma (LUAD), METTL3 triggers the oncogenic molecule c-MYC by enhancing the stability of lncRNA LCAT3, interacting with the upstream protein FUBP1, and promoting tumor cell growth, infiltration, and dissemination." (PMID 40271153, 2025).
lung adenocarcinoma (continued). "Another member of the system Xc−, SLC3A2, can also be positively regulated by METTL3 and IGF2BP3 in lung adenocarcinoma cells." (PMID 41373022, 2025). "In hepatoblastoma and lung adenocarcinoma ferroptosis is inhibited by enhancement of SCL7A11 mRNA stability by the m6A RNA guide, METTL3." (PMID 41339932, 2025). "ENO can be modulated by m6A modifiers, including METTL3, KIAA1429, WTAP, YTHDF2 and ALKBH5, mediating the cell glycolysis process in lung adenocarcinoma, breast cancer and ovarian cancer." (PMID 41373022, 2025). "What is more, according to the TCGA and CPTAC database, METTL3 was highly expressed in lung squamous carcinoma (LUSC) and lung adenocarcinoma (LUAD) at mRNA and protein levels, suggesting its role as an oncogene." (PMID 38370374, 2024). "A further study also identified METTL3, YTHDF1, and YTHDF2 as prognostic lung adenocarcinoma biomarkers." (PMID 36831575, 2023). "Similar to that in lung adenocarcinoma, LncRNA MALAT1 is also methylated and delocalized by METTL3 in Thymic epithelial tumors." (PMID 37365581, 2023). "Studies have shown that METTL3 can enhance the stability of the lncRNA ABH11-AS1 transcript, thereby enhancing the Warburg effect of lung adenocarcinoma, and ultimately promoting the occurrence and development of tumors." (PMID 35784761, 2022). "Compared with the control group, METTL3 and YTHDF1 are overexpressed in patients with lung adenocarcinoma, and the YTHDF2 is overexpressed in most cases." (PMID 34489709, 2021). "Especially, it has been demonstrated that several m6A methyltransferase, such as METTL3 and YTHDF1, facilitate lung adenocarcinoma progression by activating cell migration and invasion through m6A methylation." (PMID 33193582, 2020). "Among these genes, KIAA1429, HNRNPC, YTHDC2, METTL3, WTAP, YTHDC1, and FTO were down expressed in lung adenocarcinoma, RBM15, ZC3H13, YTHDF1, YTHDF2, and ALKBH5 were up expressed." (PMID 32398949, 2020). "For example, Methyltransferase-like 3 (METTL3), one of the m6A writers, is upregulated in lung adenocarcinoma and play oncogenic effect by promoting translation of its target mRNA transcripts including EGFR and TAZ63." (PMID 31653849, 2019). "Our analyses revealed lower abundance of METTL3 and FTO transcripts in cervical squamous cell carcinoma and endocervical adenocarcinoma (CESC), breast invasive carcinoma (BRCA), lung adenocarcinoma (LUAD), and colon adenocarcinoma (COAD) compared to their matched normal tissues." (PMID 38665783, 2024). "In addition, METTL3 increases the RNA stability and expression of SNHG17 via m6A modification in gefitinib-resistant lung adenocarcinoma." (PMID 37996892, 2023). "In lung adenocarcinoma (LUAD), miR‐600 could suppress METTL3 expression, and simultaneously METTL3 was capable of stimulating PI3K/AKT/Bcl2 pathway." (PMID 36162823, 2023). "The METTL3, YTHDF1 and YTHDF2 may be new biomarkers for the prognosis of lung adenocarcinoma." (PMID 34489709, 2021). "The increased METTL3 and decreased FTO in the present TCGA analysis indicate that the dysregulated writer and/or eraser may be responsible for the increased m6A content in lung adenocarcinoma cells." (PMID 32195181, 2020).
melanoma (72 papers, 2019 to 2026). A malignant, usually aggressive tumor composed of atypical, neoplastic melanocytes. "The m6A methyltransferase METTL3 has emerged as a systematically implicated oncogenic driver in melanoma, while its overexpression controls tumor progression by increasing proliferation, migration, and invasion." (PMID 41157107, 2025). "In skin cancers like melanoma and squamous cell carcinoma, aberrant m6A modifications are linked to tumorigenesis and progression, with dysregulation of regulators such as METTL3 and FTO enhancing tumor cell proliferation and invasion." (PMID 39472463, 2024). "METTL3, a critical m6A methyltransferase, has been implicated in the progression of numerous cancers, including melanoma." (PMID 39247584, 2024). "Recently, it has been observed that inhibition of METTL3 in a mouse melanoma model causes accumulation of dsRNA and a viral mimicry phenotype." (PMID 39221819, 2024). "Intriguingly, the therapeutic efficacy of PD-1 checkpoint blockade is robustly attenuated in METTL3-deficient mice, indicating METTL3 as a potential therapeutic target for tumor immunotherapy, including in melanoma." (PMID 35693795, 2022). "Analysis of the underlying mechanism of METTL3 suggested that it affected melanoma cell growth and invasion by regulating TXNDC5." (PMID 35117988, 2021). "Furthermore, depletion of Mettl3 in myeloid cells was associated with reduced responsiveness to anti-PD-1 therapy in melanoma B16 tumor metastasis models." (PMID 39987091, 2025). "Moreover, high METTL3 mRNA expression was significantly associated with clinical staging in melanoma." (PMID 35117988, 2021). "Nonetheless, METTL3 and METTL14 are risk genes in melanoma based on published research, while the results of this study indicated WTAP as a protective factor." (PMID 41301778, 2025). "On the contrary, multiple reports have indicated that METTL3 and METTL14 were risky and drug-resistant genes associated with melanoma." (PMID 41301778, 2025). "In this study, we discovered that inhibiting METTL3 significantly augmented the effectiveness of ICB therapy in both B16 melanoma and MC38 colon tumour models." (PMID 39568154, 2024). "On the positive side, we have found that targeting METTL3 enhances the killing effect on human melanoma cancer in vivo, and in vitro experiments showed that METTL3 inhibition can augment the killing ability of human T cells against tumours." (PMID 39568154, 2024). "Among these regulators, METTL3 modulates the migratory capabilities of melanoma cells, specifically by modifying the RNA m6A of UCK2." (PMID 39247584, 2024). "In this study, we identify that METTL3 functions as an immune suppressor that limits anti‐tumour immunity in melanoma and colon cancer." (PMID 39568154, 2024). "The inhibiting of METTL3, an RNA m6A methyltransferase, has been shown to trigger viral defense mechanisms and interferon responses within B16 melanoma cells." (PMID 39568154, 2024). "For hs294t melanoma cells, in addition to treatment with AR extracts, METTL3 was overexpressed, and a recovery experiment was performed in the AR extract treatment group." (PMID 39247584, 2024). "Taken together, these results suggest that DHPS mediates the hypusination of eIF5A by assisting METTL3 in recognizing its m6A site for methylation modification and maintaining the stability of mRNAs in melanoma cells." (PMID 38952061, 2024). "TXNDC5 is downregulated by decreasing N6-methyladenosine (m6A) levels as a post-transcriptional modification in RNA after METTL3 knockdown, ultimately inhibiting melanoma progression." (PMID 38666927, 2024). "According to the literature, METTL3 can regulate Wnt signallingpathway genes to affect the proliferation of melanoma cells." (PMID 39247584, 2024). "In melanoma tumour tissues, AR extracts regulate the expression of METTL3, affect the level of RNA m6A and downregulate the expression of genes associated with the Wnt signalling pathway." (PMID 39247584, 2024).